FBN1 (fibrillin 1)
Diseases named in the same sentence as FBN1 in open-access papers (continued):
Sharing a sentence is not in itself a finding about the gene and the disease.
Marfan syndrome (continued). "Although known FBN1 mutations are spread throughout the gene, very few genotype–phenotype correlations exist in FBN1-related Marfan syndrome." (PMID 39008115, 2024). "In Marfan’s syndrome, a hereditary connective tissue disorder, there is a deficiency of normal fibrillin-1, an essential component of microfibrils in the extracellular matrix." (PMID 38611620, 2024). "Different in vitro models derived from hPSCs with different pathogenic FBN1 variants have been established to study various aspects of the multi-organ affecting disease that is Marfan syndrome." (PMID 39830211, 2024). "Marfan Syndrome (MFS) is a connective tissue disorder due to mutations in fibrillin-1 (Fbn1), where a Fbn1 missense mutation (Fbn1C1039G/+) can result in systemic increases in the bioavailability and signaling of transforming growth factor-β (TGF-β)." (PMID 39959812, 2024). "Marfan syndrome, a hereditary disorder of connective tissue marked by FBN1 gene mutations, presents a clinical tapestry requiring a multidisciplinary approach for optimal management." (PMID 38707097, 2024). "The connective tissue protein fibrillin-1 is encoded by a gene located on chromosome 15q21 and children who have Marfan syndrome present a mutation in one of their two copies of this gene (FBN)." (PMID 39006324, 2024). "Marfan syndrome is a systemic connective tissue disorder caused by a pathogenic mutation of the FBN1 gene that encodes fibrillin-1, which is the main component of microfibrils constituting the extracellular matrix." (PMID 38919319, 2024). "Among these mRNAs and lncRNAs, FBN1 (fibrillin-1) mutations are more common in patients with aortic dissection in Marfan syndrome." (PMID 38921668, 2024). "In this cohort, FBN1 variants have been identified in two probands, associated with Marfan syndrome." (PMID 38243264, 2024). "Cytogenomic whole-genome SNP microarray analysis revealed a deletion within the FBN1 gene spanning exons 7–30, which overlapped with the exon deletion hotspot region associated with neonatal Marfan syndrome." (PMID 38791509, 2024). "Marfan syndrome is caused by pathogenic variants in FBN1, the gene encoding for the extracellular matrix protein fibrillin-1 which ensembles into microfibrils." (PMID 39830211, 2024). "Pathogenic variants in FBN1, which encodes fibrillin-1, a protein that is a major component of extracellular matrix microfibrils, are the cause of Marfan syndrome, a genetic disorder characterized by TAD, skeletal, and ocular abnormalities." (PMID 39185210, 2024). "It is also worth considering that certain fibrillin-1 fragment anomalies are associated with vascular abnormalities such as aortic dissection, which itself is a prominent feature of Marfan Syndrome from fibrillin-1 mutations." (PMID 38347040, 2024). "Marfan syndrome is caused by mutations in the fibrillin-1 gene (FBN1), which impacts multiple organ systems, including the skeleton, eyes, heart, lungs, and blood vessels." (PMID 39110386, 2024). "Impaired assembly plays a role in the molecular pathogenesis of genetic disorders caused by mutations in Fibrillin-1 (Marfan syndrome) and Fibrillin-2 (congenital contractural arachnodactyly)." (PMID 39273357, 2024). "The patient with musculoskeletal, cardiovascular, and ocular findings compatible with Marfan syndrome had an unusual pathogenic mutation on the FBN1 gene." (PMID 38826987, 2024). "Marfan syndrome is a genetic disease, with an autosomal dominant transmission, due in most cases to a variant of the gene coding for fibrin-1 (FBN1), which composes microfibrils, proteins found in the extracellular matrix." (PMID 38790247, 2024). "Pathogenic mutations in FBN1 are the cause of Marfan syndrome, a life-threatening autosomal dominant disorder of connective tissue." (PMID 38495669, 2024). "Marfan syndrome (MFS) is an autosomal dominant disease caused by FBN1 (fibrillin-1) gene mutations, and the morbidity is 1/5000 individuals." (PMID 38473909, 2024).
Marfan syndrome (continued). "Mutations of the FBN1 gene lead to Marfan syndrome (MFS), which is an autosomal dominant connective tissue disorder featured by thoracic aortic aneurysm risk." (PMID 38473909, 2024). "Previous studies have identified cryptic splicing in Marfan syndrome, involving a 111‐bp insertion and a 48‐bp deletion, both of which caused premature stop codons in FBN1, resulting in shorter FBN1 polypeptides." (PMID 39219382, 2024). "The purpose of this study is to report a 47-year-old male patient with an unusual variant in the FBN1 gene causing Marfan syndrome." (PMID 38826987, 2024). "Marfan syndrome, an autosomal dominant disorder resulting from mutations in the fibrillin-1 (FBN1) gene, leads to systemic connective tissue weakness, predominantly affecting the cardiovascular, skeletal, and ocular system." (PMID 39795873, 2024). "The cellular model for Marfan syndrome revealed changes in microfibril formation, confirming the pathogenic role of FBN1 variants." (PMID 39830211, 2024). "Marfan syndrome is a systemic inheritable connective tissue disease associated with fibrillin-1 gene mutations, which cause abnormalities in connective tissue." (PMID 38198071, 2024). "In the case of the FBN1 gene associated with Marfan syndrome and other related connective tissue disorders, mutations affecting splicing can have significant clinical implications." (PMID 39219382, 2024). "Mutations in the ADAMTSL4 gene (1q21.2), inherited in a recessive manner, and dominant mutations in the FBN1 gene (15q21.1), the same gene that causes Marfan syndrome, have been identified as causes of isolated EL." (PMID 39202561, 2024). "Marfan syndrome (MFS) is a multisystem genetic disorder with over 3000 mutations described in the fibrillin 1 (FBN1) gene." (PMID 37688493, 2024). "Our purpose is to report a patient with a novel variant in the fibrillin-1 (FBN1) gene causing the Marfan syndrome (MFS)." (PMID 38665719, 2024). "A positive result was obtained from predictive testing for a likely pathogenic FBN1 variant in a patient whose son was diagnosed with Marfan syndrome-related aortic dissection." (PMID 39669619, 2024). "Heterozygous FBN1 mutations in the gene coding for this protein predispose to ATAAD in patients with Marfan syndrome." (PMID 38700707, 2024). "We highlighted the importance of specific FBN1 variants and higher systemic scores in identifying the potential for intrinsic cardiomyopathy in pediatric patients with Marfan syndrome." (PMID 39379624, 2024). "In the majority of cases (8/10), de novo mutations in the FBN1 gene were detected and correlated with the Marfan syndrome phenotype." (PMID 39456956, 2024). "Marfan syndrome is linked to mutations in the fibrillin 1 (FBN1) gene, which is essential for the microfibrils that support elastin fibers and maintain vessel wall integrity." (PMID 39410571, 2024). "Marfan syndrome (MFS) is an autosomal dominant connective tissue disorder caused by missense mutations in fibronectin-1 (FBN-1), a component of extracellular microfibrils." (PMID 39402049, 2024). "In humans, mutations in FBN1 can cause Marfan syndrome (MFS), one of the most extensively studied connective tissue disorders that impact the musculoskeletal, cardiovascular, pulmonary, ocular, and craniofacial organs." (PMID 38844137, 2024). "Pathogenic FBN1 variants are linked to Marfan’s syndrome (MFS) and mitral valve–aorta–skeleton–skin (MASS) syndrome." (PMID 36675070, 2023). "Although FBN1 mutations play a central role in the clinical manifestations of Marfan syndrome, fibrillin-2 (FBN2) mutations have also been shown to potentially cause the disease." (PMID 37332582, 2023). "One of these heritable forms of TAA is Marfan syndrome, which results from an autosomal dominant mutation in the fibrillin-1 (FBN1) gene." (PMID 37686377, 2023).
Marfan syndrome (continued). "Marfan syndrome (MFS) is an inherited connective tissue disorder caused by heterozygous mutations in the FBN1 gene, which encodes the extracellular matrix protein fibrillin-1." (PMID 37270806, 2023). "As such, mutations in the FBN1 gene can cause a wide variety of genetic diseases such as Marfan syndrome, an autosomal dominant disorder characterized by ocular, skeletal and cardiovascular abnormalities." (PMID 38269088, 2023). "Marfan syndrome is primarily due to variants in the gene FBN1, encoding the connective protein fibrillin-1, that alter the transforming growth factor β (TGFβ) pathway." (PMID 36873395, 2023). "Genetic variants were identified in four genes: FBN1 (associated with Marfan syndrome and cardiovascular complications; n = 6), ADAMTSL4 (associated with non-syndromic ectopia lentis; n = 2), LTBP2 (n = 1) and ASPH (n = 1)." (PMID 37107549, 2023). "Coincidently, Marfan syndrome patients with cysteine residue modifying mutations of the fibrillin-1 calcium binding epidermal growth factor like domain all showed sign of retinal detachment or ectopia lentis." (PMID 37001705, 2023). "The study of fibrillin-1 mutations associated with Marfan syndrome has highlighted the prominent role of the TGFβ pathway in MVP." (PMID 36873395, 2023). "Mutations in FBN1 can therefore lead to improper TGFβ sequestration, subsequently changing TGFβ availability and signaling, and ultimately resulting in development of Marfan syndrome." (PMID 37325472, 2023). "Mutations in the fibrillin-1 gene result in Marfan syndrome (MFS), an autosomal dominant disease of the connective tissue." (PMID 37159453, 2023). "The most representative are the Marfan syndrome linked to pathogenic variants in the FBN1 gene (encoding fibrillin-1) and several disorders related to the Marfan syndrome (notably Loeys-Dietz syndrome) involving an alteration of the TGF-β signaling pathway." (PMID 40225146, 2023). "Since Marfan syndrome (OMIM: 154700) is caused by a heterozygous loss-of-function mutation of the FBN1 gene, we analyzed lumbar IVDs in patients with Marfan syndrome." (PMID 36966180, 2023). "Compare to Marfan syndrome carrying FBN1 mutation, MV involvement is less frequent in LDS type 2: MVP was found in 21 vs. 45% of patients (P = 0.001), MR in 35 vs. 56% (p < 0.0001) and referral to MV surgery was rare in TGFBR2 patients." (PMID 36873395, 2023). "Marfan syndrome (MFS) is a connective tissue disorder associated with a defect in the fibrillin 1 protein." (PMID 37584655, 2023). "Several murine models of genetic TAA have been studied, including Marfan syndrome (FBN1 mutations), Loeys-Dietz syndrome (TGFBR1, TGFBR2 mutations) and familial TAA associated with ACTA2 mutations." (PMID 36675309, 2023). "It is notable that fibrillin-1 is encoded by the FBN1 gene, in which pathogenic variants cause Marfan syndrome and/or ectopia lentis, and SCAD has been described in individuals with Marfan syndrome [32•]." (PMID 37979122, 2023). "Five children with FBN1-associated ectopia lentis (presumed Marfan syndrome) were identified in this cohort." (PMID 37107549, 2023). "FBN1 variants are known to cause connective tissue disorders, including Marfan syndrome and stiff skin syndrome through alterations of the ECM." (PMID 37372943, 2023). "Marfan syndrome is caused by mutations in the fibrillin-1 gene (FBN1), and, among other abnormalities, patients with this syndrome exhibit dilatation of the aortic sinus with an increased risk of type A aortic dissection." (PMID 38169687, 2023). "Marfan syndrome (MFS) is an autosomal dominant disorder caused by a heterozygous mutation of the FBN1 gene." (PMID 37445606, 2023). "In Marfan’s syndrome, which is frequently associated with the development of AA, mutations in fibronectin 1 (FBN1) occur." (PMID 36737432, 2023).
Marfan syndrome (continued). "The region across the TB5 and cbEGF18 domains in FBN1 is commonly called the “neonatal” region due to its susceptibility to mutations that result in an extremely severe form of neonatal Marfan syndrome." (PMID 38269088, 2023). "Marfan syndrome (MFS) is a disorder of genetic origin with an autosomal dominant character that affects the gene that encodes for the fibrillin-1 protein (FBN-1), therefore altering connective tissue." (PMID 35082968, 2022). "Mutations in fibrillin-1 give rise to a spectrum of disorders associated with dysregulated TGFβ signalling termed fibrillinopathies, the most common of which is Marfan syndrome (MFS)." (PMID 35122964, 2022). "Marfan syndrome is a genetic disorder, usually caused by pathogenic variants in the fibrillin-1 (FBN1) gene that causes progressive enlargement of the aortic root." (PMID 36049495, 2022). "Mutations in PRSS56 cause nanophthalmos or autosomal-recessive posterior microphthalmos; mutations in FBN1 have been linked to Marfan syndrome (MFS) and Weill–Marchesani syndrome, both of which are characterized by high myopia and ectopia lentis." (PMID 35285860, 2022). "FBN1 variants were also associated with Marfan syndrome’s skeletal features, autosomal dominant disorder, which frequently requires orthopedic surgical intervention." (PMID 35526034, 2022). "A porcine model for Marfan syndrome based on an FBN1 mutation (+/Glu433AsnfsX98) has been established using genome editing and somatic cell nuclear transfer technologies." (PMID 35887698, 2022). "Marfan syndrome is an autosomal dominant genetic condition caused by mutations in FBN1 or FBN2 genes." (PMID 36295040, 2022). "Marfan syndrome is an autosomal-dominant disorder caused by mutations in the gene encoding fibrillin-1." (PMID 35321745, 2022). "Several mouse models were created to mimic Marfan syndrome, in which patients develop TAAs due to Fibrillin-1 deficiency." (PMID 35492343, 2022). "Marfan syndrome (MFS) results from a mutation of the FBN1 gene that encodes for fibrillin-1, a structural protein that is a component of the microfibrils in the extracellular matrix (ECM)." (PMID 35560311, 2022). "It is usually felt that only the aorta is affected in Marfan syndrome with an FBN1 mutation, or that, if other arteries dilate, this is usually the consequence of aortic dissection." (PMID 35360038, 2022). "Marfan syndrome is almost exclusively inherited in an autosomal-dominant manner, although rare case reports have described recessive fibrillin 1 gene (FBN1) mutations." (PMID 35601426, 2022). "Marfan syndrome was first mimicked in Fbn1mgΔ/mgΔ mice, with an in-frame deletion of exons 19–24 in the Fbn1 gene causing severe (ten-fold) reduction of Fbn1 expression." (PMID 35492343, 2022). "Marfan’s syndrome type 1 is caused by mutations in the FBN1 gene that encodes the extracellular matrix protein fibrillin-1 protein." (PMID 36292765, 2022). "In this study, we report a cysteine to tyrosine substitution in two different domains of fibrillin-1, both of which cause Marfan syndrome with ocular abnormalities, in two families." (PMID 36035136, 2022). "Whole exome sequencing (WES) study revealed heterozygous variant c.5187G>A p.(Trp1729*) in gene FBN1 - pathogenic for Marfan syndrome." (PMID 36262952, 2022). "Marfan syndrome (MFS) is one of the most common inherited disorders of connective tissue caused by mutations of the fibrillin-1 gene (FBN1)." (PMID 35887698, 2022). "Marfan Syndrome (MFS) is an autosomal dominant disorder of the connective tissue that is caused by mutations in the FBN1 gene encoding fibrillin-11,2." (PMID 36577770, 2022). "Mutations in the fibrillin-1 gene are associated with cardiovascular, ocular, and skeletal abnormalities in Marfan syndrome." (PMID 36291539, 2022).
Marfan syndrome (continued). "Marfan syndrome (MFS) is associated with FBN1 mutations; Ehlers–Danlos syndrome (EDS) is relevant to the COL3A1 mutation; Loeysؘ–Dietz syndrome (LDS) is related to TGFBR1 or TGFBR2 mutations as well as SMAD3 or TGFB2 mutations." (PMID 36291545, 2022). "Marfan Syndrome (MFS) is an autosomal dominant condition caused by variants in the fibrillin-1 (FBN1) gene." (PMID 35741789, 2022). "Marfan syndrome (MFS) is an autosomal dominant connective tissue disorder associated with the mutation of the FBN1 gene." (PMID 36059296, 2022). "In Marfan syndrome, a primary hereditary connective tissue disorder, PE is considered a clinical manifestation of the inherited fibrillin-1 deficiency." (PMID 35268332, 2022). "Mutations in genes encoding for EGFDs of fibrillin-1 are associated with Marfan syndrome, a connective tissue disorder, and mutations in EGFDs of factor IX are associated with hemophilia B, a blood clotting disease." (PMID 35700824, 2022). "ES revealed a pathogenic heterozygous nonsense variant c.2649G > A (p.Trp883Ter) in FBN1, which is associated with Marfan syndrome (MIM:154700)." (PMID 35346302, 2022). "Mutations in fibrillin-1 cause pleiotropic manifestations in Marfan syndrome (MFS), including dissecting thoracic aortic aneurysms, myocardial dysfunction, progressive bone loss, disproportionate skeletal growth, and the dislocation of the crystalline lens." (PMID 35163812, 2022). "The Marfan syndrome mutation N2144S in the FBN1 EGF-like repeat led to a conformational shift impacting the 2 nearest intrachain disulfide bonds." (PMID 36214621, 2022). "The type-1 Marfan syndrome (MFS) is an autosomal dominant fibrillinopathy linked to a mutation in the fibrillin-1 (FBN1) gene." (PMID 35216218, 2022). "One widely studied exception is Marfan syndrome (MFS) in which mutations in the extracellular protein fibrillin-1 cause additional abnormalities in the heart, eyes, and skeleton." (PMID 35053276, 2022). "Animal models of Marfan syndrome with mutations that reduce the amount of fibrillin-1 produced to display a reduction in cleaved aggrecan compared with wild-type mice." (PMID 36012466, 2022). "In contrast to being upregulated after TGFβ-1 (10 ng / mL) treatment, the ligand-receptor pair fibrillin 1 (fbn1) - integrin alpha-V (Itgav) was significantly downregulated after ALKi treatment: Fbn1 mutations are the main cause for Marfan Syndrome." (PMID 36193159, 2022). "This is particularly interesting as FBN1 is the causative gene of the inherited connective tissue disorder Marfan syndrome." (PMID 35457215, 2022). "In Marfan syndrome, however, the inability to properly code for the protein fibrillin-1 prematurely leads to the degradation and loss of elastin fiber integrity in the ECM." (PMID 35560311, 2022). "Marfan syndrome results from mutations to the gene that encodes fibrillin-1, a glycoprotein that appears to help confer the normally long half-life of elastic fibers." (PMID 36315608, 2022). "Marfan syndrome is caused by mutations of the fibrillin-1 gene, which weakens the connective tissue integrity." (PMID 34757469, 2022). "Marfan syndrome results from mutations in the fbn1 gene encoding fibrillin-1, an extracellular matrix protein." (PMID 34198563, 2021). "We found that FBN1 regulated by hsa-miR-339-5p is the causative gene of a variety of genetic diseases, including fibrinopathy and Marfan syndrome." (PMID 34926471, 2021). "Here, we identified 11 potential disease-causing FBN1 variants in patients with Marfan syndrome, and six of them are novel." (PMID 34957211, 2021). "The identification of pathogenic missense variants in the FBN1 gene in two patients with Marfan syndrome in 1991 provided final confirmation." (PMID 34336739, 2021). "Mutation of FBN1 causes Marfan syndrome and about 2% of Marfan patients are affected by a not-categorized type of glaucoma." (PMID 34299278, 2021).